ATM (ATM serine/threonine kinase)
Diseases named in the same sentence as ATM in open-access papers (continued):
Sharing a sentence is not in itself a finding about the gene and the disease.
thyroid cancer (26 papers, 2015 to 2025). "Genes related to thyroid cancer development are involved in DNA repair, ATM (ataxia–telangiectasia mutated) signaling, RET (receptor tyrosine kinase) signaling, and the regulation of thyroid activity (FOXE1, NKX2-1, TSHR)." (PMID 40361383, 2025). "Studies on ATM gene polymorphisms in the context of thyroid cancer have shown different results depending on the population studied." (PMID 38892180, 2024). "To explore the effects of ATM on the pro-tumoral effects of pathogenic mutations in driver genes, we established ATM knock-down thyroid cancer cell lines (B-CPAP, TPC-1, Cal-62 and Nthy-ori-3-1)." (PMID 38886866, 2024). "We found a significant association between the presence of truncating variants c.5932G>T and c.4148C>A in the ATM gene and the development of other primary tumors besides BC (colorectal or thyroid cancer), with an OR= 8.8 (p = 0.01)." (PMID 39684352, 2024). "A meta-analysis summarizing the importance of ATM polymorphisms and the risk of thyroid cancer was found." (PMID 38892180, 2024). "An ATM truncating variant was found in a patient with bilateral BC and a previous thyroid cancer; moreover, other cancer cases are reported within her family." (PMID 36035419, 2022). "An increased incidence of thyroid cancer was observed in obligate ATM mutation carriers (RR adjusted = 2.6)." (PMID 33218058, 2020). "Association between ATM expression and clinicopathological features of thyroid cancer was also analyzed." (PMID 25861265, 2015). "Thus, ATM deficient thyroid cancer cells bearing BRAFV600E, KRASG12R or CCDC6-RET displayed higher proliferative ability, lower apoptotic rate and greater aggressiveness than NC-transfected cells in vitro." (PMID 38886866, 2024). "Additionally, a dose-response relationship was observed between the number of ATM-risk alleles and the risk of thyroid cancer (p = 0.01)." (PMID 38892180, 2024). "In the ATM gene (NM_000051), a nonsense variant [c.1463G > A, p.(Trp488Ter)–rs879254093] in the exon 10 was found in a female patient affected by bilateral BC and also by a thyroid cancer (P12)." (PMID 36035419, 2022). "Later, selective mutations in the ATM gene are related to thyroid cancer." (PMID 33218058, 2020). "In addition, a possible association between breast and thyroid cancer was highlighted by the identification of two ATM carriers among the sporadic cancer patients with breast/thyroid cancer (2/69, 2.9 %), encouraging for further studies." (PMID 27599564, 2016). "Two individuals with ATM variants were identified among breast/thyroid cancer cases (2/69, 2.9)." (PMID 27599564, 2016). "Some other researches demonstrated that ATM polymorphisms might be involved in the development of thyroid cancer." (PMID 25861265, 2015). "In addition, the G allele of ATM rs189037 exhibited a protective effect against thyroid carcinoma." (PMID 29928473, 2018). "This resulted in decreased proliferation of thyroid cancer; 2) induced ROS-mediated DNA damage and activation of ATM/CHK2, leading to the arrest of G1/S phase transition and increased apoptosis in thyroid cancer." (PMID 40007997, 2025). "Thyroid cancer (TC) has also been associated with the presence of germline mutations in BRCA2 and ATM genes." (PMID 38890714, 2024). "We show that the PIKK proteins are viable therapeutic targets in human thyroid cancers, as PIKKs were highly expressed across classifications, with ATM scoring consistently lower." (PMID 27527858, 2016). "PIKKs were highly expressed across human thyroid-carcinoma classifications, with ATM scoring consistently lower." (PMID 27527858, 2016).
thyroid cancer (continued). "In thyroid cancer group, both ATM and γH2AX were highly expressed in 45 cases and lowly expressed in 36 cases." (PMID 25861265, 2015). "γH2AX and ATM expressed higher in thyroid cancer tissues than in benign nodular goiter and normal adjacent tissues." (PMID 25861265, 2015). "Statistically significant differences were also found in ATM expression among different pathologic types of thyroid cancer." (PMID 25861265, 2015). "In this study, γH2AX and ATM showed increased expression in thyroid cancer tissues as compared with benign tissues." (PMID 25861265, 2015). "Overall, both γH2AX and ATM were supposed to influence thyroid hormones and γH2AX has been proved to play a role in the differentiation status of thyroid cancer." (PMID 25861265, 2015). "This study aims to investigate ATM and γH2AX expression in thyroid cancer and discuss possible relationship between thyroid function tests and DNA damage." (PMID 25861265, 2015). "It is inappropriate to come up with a distinct correlation between ATM expression and differentiation of thyroid cancer." (PMID 25861265, 2015). "In this study, γH2AX and ATM expressed higher in well differentiated thyroid cancer tissues as compared to poorly differentiated thyroid cancer, which was consistent with the researches above." (PMID 25861265, 2015). "Different pathologic type of thyroid cancer tissues showed different expression level of ATM, with statistically significant differences (P = 0.05)." (PMID 25861265, 2015). "Anaplastic thyroid cancer tissues showed higher ATM expression than well differentiated thyroid cancer tissues, while the latter showed higher ATM expression than poorly differentiated thyroid cancer tissues." (PMID 25861265, 2015). "The presence of the ATM haplotype (C-G-T) +/- was associated with a lower risk of PTC compared to the absence of this haplotype (C-G-T) -/-, suggesting the potential role of ATM genetic polymorphisms in thyroid cancer development in the Korean population." (PMID 38571492, 2024). "The cell model experiment illustrated that the ATM signaling pathway might be involved in thyroid cancer cell death." (PMID 37745716, 2023). "Furthermore, we explored the underlying mechanism of DNA damage/ATM/CHK2 mediated G1/S phase transition arrest, and the relationship between SGLT2 and cell cycle protein in thyroid cancer." (PMID 35148777, 2022). "Different studies demonstrated different roles of ATM in thyroid cancer." (PMID 25861265, 2015). "ATM expression was correlated with γH2AX expression in thyroid cancer in this study." (PMID 25861265, 2015). "However, why anaplastic thyroid cancer tissue showed higher ATM expression than poorly differentiated thyroid cancer remains to be a problem." (PMID 25861265, 2015). "Therefore both of ATM and γH2AX seem to correlate with thyroid hormones and γH2AX plays a role in the differentiation status of thyroid cancer." (PMID 25861265, 2015). "The effect of caffeine (inhibitor of ATM and ATR) and UCN-01 (CHK1 inhibitor) was evaluated in cell cycle progression of thyroid cancer cells after γ‐radiation or doxorubicin treatment." (PMID 38380364, 2024). "Therefore, canagliflozin induced ROS-mediated DNA damage and ATM/CHK2 activation, which lead to G1/S phase transition arrest and increased apoptosis in thyroid cancer." (PMID 35148777, 2022).
thyroid cancer (continued). "In human thyroid cancer cells, SLC26A4-AS1 silencing enhances the interaction between DDX5 and the transcription factor E2F1; then, the DDX5-E2F1 complex binds to the MRN gene promoter and thus stimulates the MRN/ATM-dependent DNA DSB signaling cascade and thyroid cancer metastasis." (PMID 35992805, 2022). "Thus we proposed that γH2AX was correlated with differentiation of thyroid cancer while ATM was not correlated with differentiation of thyroid cancer distinctly." (PMID 25861265, 2015). "However no distinct correlation has been found between ATM expression and differentiation of thyroid cancer." (PMID 25861265, 2015). "However, the results showed that both of ATM and γH2AX were correlated with FT3 in thyroid cancer." (PMID 25861265, 2015). "However, the role of ATM and γH2AX in thyroid cancer has not been completely elucidated." (PMID 25861265, 2015).
viral infection (25 papers, 2009 to 2025). "As counteracting ATM deficiency may restore T-cell competency during viral infection and prevent premature immune aging, these studies may provide new strategies to improve immunotherapy and vaccine responses against human viral diseases." (PMID 29644094, 2018). "Viral infection often trigger an ATM serine/threonine kinase (ATM)-dependent DNA damage response in host cells that suppresses viral replication." (PMID 38177923, 2024). "In the case of JCV, besides our study described here, there is one other report of the activation of ATM by viral infection." (PMID 28202068, 2017). "We sought to separate these functions of ATM by varying the time period of viral infection during which ATM inhibitor was applied." (PMID 25474690, 2014). "One example of DNA damage signaling activated by virus infection is seen in the case of EBV infections, where infection induces the cellular DNA damage response and activates the ataxia telangiectasia-mutated (ATM) signal transduction pathway." (PMID 25340830, 2014). "Again, further investigations are needed to document the role of ATM during the viral infection process, but it is likely that the RIANS model may contribute to understanding the basic mechanisms and to predicting the cases at risk." (PMID 36900274, 2023). "In addition to its response to and repair of DSBs raised from the host cell genomes, the MRN complex can bind to a viral genome and activate the ATM-mediated pathway during viral infection." (PMID 34440334, 2021). "Because the immune system is in constant turnover during viral infection, with high demands for lymphocyte replenishment to maintain the equilibrium of the T cell compartment, insufficient activation of ATM would be expected to affect both primed and unprimed T cells." (PMID 31781094, 2019). "As UL76 is required for maximal IL-8 induction by HCMV and HCMV infection activates ATM, we hypothesized that ATM would also have a role in IL-8 up-regulation during viral infection." (PMID 24068928, 2013). "The importance of ATM activity in SV40 chromatin replication suggested the possibility that other checkpoint kinases might also contribute to viral infection." (PMID 23592994, 2013). "A number of mechanisms have been proposed for how viral infections lead to ATM activation." (PMID 21589897, 2011). "Overexpressed in cytoplasm during viral infection, the Spike protein appears to be a potential X-protein that may sequestrate ATM and drastically reduce the diffusion of ATM monomers in the nucleus to respond to DNA strand breaks induced by the viral infection." (PMID 36900274, 2023). "The ATM—Chk2 pathway principally responds to DNA double-strand breaks, whereas the ATR—Chk1 pathway responds to a broad range of DNA abnormalities caused by ultra-violet light, DNA replication block, virus infection, interstrand DNA crosslinking, and double-strand break end resection." (PMID 26727128, 2016). "Upon viral infection, the MRN complex recognizes and binds to viral DNA, triggering local ATM activation." (PMID 39752632, 2025). "Since E4orf4 appears to inhibit the ATM- and ATR-regulated DDR and DDR was suggested to be detrimental to Ad infection, we examined the contribution of E4orf4 and the DDR components ATM and ATR to the efficiency of virus infection." (PMID 26867009, 2016). "Importantly, the intricate interplay between IE1, the MRN complex, and ATM pathway activation will need to be studied in a spatiotemporal manner to elucidate when and how IE1 manipulates this important pathway during viral infection and integration." (PMID 38177923, 2024).
viral infection (continued). "Our results together with the lengths to which Ad goes to inhibit ATM and ATR signaling, strongly suggest that both ATM and ATR can inhibit Ad replication, at least under some conditions, and that their elimination is therefore important for efficient virus infection." (PMID 26867009, 2016). "Viral infection by BKPyV did cause severe DNA damage in the absence of ATM or ATR, and as previously noted, numerous animal and plant studies have shown that ATM and ATR play central roles in DNA damage repair." (PMID 24699527, 2014). "Importantly, ectopic overexpression of ATM is necessary and sufficient to repair the DNA damage, survival defect, and cell dysfunctions in HCV-derived T cells, thus providing a new strategy to improve immunotherapy and vaccine responses against human viral diseases." (PMID 29644094, 2018).
hereditary cancer (24 papers, 2014 to 2025). Malignant neoplasms occurring in families at a rate greater than that expected by chance and caused by germline mutations in a specific gene. "Dedicated hereditary cancer gene panel testing confirmed that the ATM p.R1875* pathogenic variant was germline in origin." (PMID 38898688, 2024). "These atypical cancers were diagnosed in a significant proportion of patients with ATM-associated hereditary cancer susceptibility in our cohort." (PMID 36865800, 2023). "Skaro et al27 reported that deleterious germline variations of hereditary cancer genes (eg, ATM, BRCA2, PALB2) were found in patients with IPMN associated with concurrent invasive cancer." (PMID 35171259, 2022). "The mother is a known carrier of the ataxia-telangiectasia mutated (ATM) gene through genetic testing for familial cancer." (PMID 35741767, 2022). "At least one VUS was identified in all genes tested by the two versions of the hereditary cancer panel, with most variants detected in the ATM gene where 59 unique variants were found in 88 individuals (7.3%)." (PMID 31159747, 2019). "There was another patient diagnosed at 48 years with invasive ductal carcinoma and positive history of familial cancer carrying the ATM c.43del variant." (PMID 31658756, 2019). "Improving the detection of ATM-associated hereditary cancer is clinically meaningful as it can enable cascade genetic testing for family members who are at risk, facilitate appropriate cancer surveillance for those affected, and prompt the use of precision-based therapies." (PMID 36865800, 2023). "In this review, we discuss the current knowledge related to the structure of the ATM gene, function of ATM kinase, clinical significance of ATM germline pathogenic variants in patients with hereditary cancers, and ongoing efforts to target ATM for the benefit of cancer patients." (PMID 35008949, 2022). "Taken together, these observations suggest that the lesion R805X could be associated with a high risk to develop tumors; moreover, ATM pathogenic germline lesions could be considered possible markers for familial cancer." (PMID 35347810, 2022). "In this review, we summarize the molecular biology of ATM, clinical significance of ATM germline PVs in patients with hereditary cancers, and new therapeutic strategies for ATM-related cancers." (PMID 35008949, 2022). "We identified deleterious heterozygous germline mutations in well-established familial cancer-associated genes, BRCA2, PALB2, ATM and MLH1, in 14.5% (8/54) of our FPC patients." (PMID 27732944, 2016). "Analysis of hereditary cancer cases (732 BC patients, 189 CRC patients, and 490 cancer-free elderly controls) revealed that 1% presented concurrent germline pathogenic variants in BRCA1, BRCA2, MUTYH, ATM, CHECK2, NBN, and RAD50." (PMID 37628631, 2023). "Germline mutations of ATM such as K1992T, G2023R, and L2492R have uncertain significance; therefore, their role in hereditary cancer is not well defined." (PMID 35347810, 2022). "This evidence has also been bolstered by a recent study demonstrating a high prevalence of germline pathogenic variants in ATM relative to other hereditary cancer genes across a spectrum of cancers lacking testing guidelines, including bladder, brain, esophagus, and head and neck cancers." (PMID 36865800, 2023).